MTOR (mechanistic target of rapamycin kinase)
Diseases named in the same sentence as MTOR in open-access papers (continued):
Sharing a sentence is not in itself a finding about the gene and the disease.
renal carcinoma (continued). "In‐depth research on the regulatory mechanisms of the PI3K/AKT/mTOR pathway in renal cancer holds immense potential in elucidating the molecular pathological mechanisms of renal cancer and developing new therapeutic strategies and drug targets." (PMID 39092291, 2024). "In vitro experiments demonstrated that PYCR1 and PYCR2 enhanced the proliferation and migration of renal carcinoma cells by activating the mTOR pathway, at least in part." (PMID 39125668, 2024). "Abnormal activation of the PI3K/AKT/mTOR pathway correlates significantly with the occurrence, invasion, and metastasis of renal cancer." (PMID 39092291, 2024). "Our study investigated the autophagy-promoting effects of RAC on 786-O and A498 cells by inhibiting the PI3K/AKT/mTOR pathway, for the development of a drug to treat renal cancer." (PMID 38764054, 2024). "Varying proline concentrations showed similar effects, indicating that PYCR1 and PYCR2 activate mTOR via proline synthesis, influencing renal cancer cell proliferation and migration." (PMID 39125668, 2024). "Further research indicates that capsaicin activates the AMPK/mTOR signaling pathway to induce autophagy in renal cancer cells, thereby reducing tumor proliferation, invasion, and epithelial-mesenchymal transition (EMT)." (PMID 39027665, 2024). "The PI3K/AKT/mTOR signaling pathway is critically involved in the pathogenesis and progression of renal cancer." (PMID 39092291, 2024). "Examining their impact on renal cancer cells, we focus on their regulation of the mTOR signaling pathway." (PMID 39125668, 2024). "Studies have further shown that TFEB affects the biological progression of renal cancer by acting on the mTOR pathway and positively correlates with the expression of PD-L1." (PMID 38730456, 2024). "Considering PYCR1, PYCR2, and HF effects on the mTOR pathway, these findings suggest targeting proline metabolism, especially via HF-mediated inhibition, as a potential therapeutic approach for renal cancer." (PMID 39125668, 2024). "Several small molecule inhibitors targeting HIF, VEGFR, and mTOR have entered clinical trial phases, potentially providing new hope for advanced renal cancer patients." (PMID 39092291, 2024). "The PI3K/AKT/mTOR pathway, frequently hyperactivated in renal cancer, contributes to cancer cell survival, growth, and invasiveness." (PMID 39092291, 2024). "The PI3K/AKT/mTOR signaling pathway plays a pivotal role in the initiation and progression of renal cancer." (PMID 39092291, 2024). "Since the development of renal carcinoma has been observed to be linked with defects in the VEGF and mTOR pathways, drugs capable of blocking travel signals through these channels are an effective treatment for renal carcinoma." (PMID 37843642, 2023). "Everolimus is an MTOR-targeted drug that plays an important role in the targeted therapy of renal cancer." (PMID 36825082, 2023). "The phosphoinositide 3-kinase-AKT-mammalian target of the rapamycin (PI3K/AKT/mTOR) signaling pathway is usually dysregulated in various cancer types including renal cancer." (PMID 37176098, 2023). "In renal carcinoma, circ_0072309 sponged miR-100 and a downregulation of this circRNA caused miR-100 increased activity which leads to activation of PI3K/AKT and mTOR pathways, important cancer-related pathways." (PMID 35805051, 2022). "Treatment with everolimus, the mTOR inhibitor which is clinically used for patients with renal cancer, successfully inhibited the activation of mTOR and the signaling of its downstream ribosomal protein S6 kinase β‐1 in OSPa and OS5K cells equally." (PMID 34133843, 2022). "It has been observed that stimulation of mTOR signaling produces EMT to enhance renal cancer cell invasion." (PMID 36471885, 2022).
renal carcinoma (continued). "In contrast, multiple pathways associated with KIRC development and metastasis, such as renal carcinoma, ERBB signaling pathway, MTOR signaling pathway, adherens junctions, tight junction, apoptosis, and focal adhesion were downregulated in low‐risk group." (PMID 35373928, 2022). "Analysis of five patients with renal cancer who responded to an mTOR inhibitor revealed alterations in TSC1 and MTOR, possibly associated with exceptional response." (PMID 36045401, 2022). "The metabolic protein expression pattern, metabolite content, mTOR, and metabolic inhibitor sensitivity of renal carcinoma cell lines were also studied and compared with tubular epithelial cells, as “normal” control." (PMID 36142502, 2022). "In a recent study found that up-regulation of miRNA-205-5p exerted an antitumor effect accomplished by decreasing VEGFA and inactivating PI3K/Akt/mTOR in renal carcinoma cells." (PMID 35669244, 2022). "TEM was developed as an mTOR-targeted anti-cancer drug in a patient with renal cancer and has been administered intraperitoneally in many studies." (PMID 36077620, 2022). "Due to no available standardized systemic diagnosis or management options for nccRCC, conventional renal cancer treatments such as mTOR, TKIs, chemotherapy and immune checkpoint inhibitors remain the main therapies." (PMID 35017463, 2022). "Although mTOR targeting is clinically approved for treatment of renal cancers, overall survival for AA renal cancer patients compared to CA counterpart has not been improved." (PMID 33996789, 2021). "A successful example is the use of the mammalian target of rapamycin(mTOR) inhibitor everolimus as second-line after treatment with sunitinib, which showed some efficacy in a model of renal carcinoma." (PMID 33921099, 2021). "EGFR is an upstream regulator of mTOR and ERK-1/2 signaling cascade and its overexpression and aberrant mutational status have been reported in several human cancers including renal cancer." (PMID 33996789, 2021). "The data confirmed that DUXAP9 is an important mediator in the Akt regulatory network, activating PI3K to induce Akt/mTOR signaling in renal cancer cells." (PMID 34168980, 2021). "mTOR is another essential kinase whose targeting has shown improved clinical efficacy against renal carcinoma." (PMID 33996789, 2021). "LGALS1 is a potentially useful biomarker for renal cancer and is implicated in tumor progression and poor outcomes through the HIF/mTOR signaling axis in RCC patients." (PMID 34688260, 2021). "In this study, we demonstrate that a novel combination of RAPA + Honokiol can effectively down-regulate the Ras-mTOR pathway to inhibit renal cancer cell growth; and it also inhibits PD-L1 expression to promote immune-mediated killing of renal cancer cells." (PMID 32635337, 2020). "mTOR has significant cross-talk with the Ras pathway, which is hyperactive in renal cancer cells, possibly through the induction of receptor tyrosine kinases (like, c-Met, EGFR (Epidermal Growth Factor Receptor) etc.)." (PMID 32635337, 2020). "Our data suggest that combining acarbose with anti-PD-1 or targeted mTOR inhibitors improves therapeutic responses in mice with renal cancer." (PMID 33036247, 2020). "RAPA, the mTOR inhibitor, is used for the treatment of renal cancer patients; it is also being used for transplant patients to prevent allograft rejection." (PMID 32635337, 2020). "To further explore the involvement of mTOR signaling in CDK1-dependent translational control, we analyzed MEFs overexpressing either WT mTOR or hyperactive mTOR mutants derived from renal cancer." (PMID 32040547, 2020). "mTOR acts as a pathological signal for several renal diseases, including glomerular disease, polycystic kidney disease, and renal cancer, and mTOR inhibitors were shown to have therapeutic effects in some renal diseases." (PMID 32276645, 2020).
renal carcinoma (continued). "To conclude, we provide the first report, to our knowledge, that the antidiabetic agent acarbose can impede renal tumor growth, promote anti-tumor immunity, and improve outcomes to anti-PD-1 and mTOR inhibitor-based therapeutics in preclinical renal cancer." (PMID 33036247, 2020). "Together, our observations suggest a novel combination therapy using RAPA + Honokiol that can effectively inhibit c-Met-induced and Ras-mTOR-mediated pathway(s) to restrict renal cancer growth as well as the immune escape of tumor cells." (PMID 32635337, 2020). "Noteworthy, the phosphorylation of downstream protein of the mTOR pathway 4EBP1 is decreased by vorinostat and fluvastatin co-treatment, and it reduced renal cancer viability." (PMID 32626692, 2020). "A potential tumor-suppressive role mediated by mTOR pathway was attributed to miR-99a, since this miRNA has been shown to be strongly downregulated in renal cancer tissues and correlated with poor survival in RCC patients." (PMID 33207823, 2020). "In more detail, the anti-cancer activity of the HDAC inhibitor vorinostat was less evident because of the intrinsic activation of the mTOR pathway in a renal cancer cell model." (PMID 32626692, 2020). "c-Met is a known inducer of Ras, which is hyper-active in renal cancer; and Ras has cross-talk with mTOR." (PMID 32635337, 2020). "In our orthotopic renal cancer model, we observed that acarbose improved therapeutic responses to both anti- PD-1 checkpoint blockade and the mTOR inhibitor rapamycin." (PMID 33036247, 2020). "This is the first study to indicate PKM2/AKT/mTOR as an important regulatory axis mediating the changes in the metabolism of renal cancer cells." (PMID 31717694, 2019). "Metastasis of renal cancer cells was prevented by inducing autophagy via the AMPK/mTOR signaling pathway through using thymoquinone." (PMID 31737173, 2019). "In this direction, we investigated the consequences of PKM2 knockdown to the mTOR pathway in renal cancer cells." (PMID 31717694, 2019). "In renal cancers, activation of autophagy with mTOR inhibitor everolimus shows antitumor effects, whereas combination of chloroquine to block the fusion of autophagosomes and lysosomes potentiates the antitumor effects of everolimus." (PMID 31061682, 2019). "CFM-4.16 was also superior in inhibiting growth of parental and mammalian target of rapamycin (mToR) inhibitor Everolimus-resistant renal cancer cells (RCC) in vitro and in vivo." (PMID 30038713, 2018). "Cho and colleagues tested the antitumor efficacy of NVP-BEZ235, a dual PI3K/mTOR inhibitor, alone or in combination with sorafenib in renal cancer xenografts." (PMID 30510618, 2018). "mTOR inhibitors proved highly successful in prolonging progression-free survival in breast cancer and renal cancer, albeit with considerable side-effects." (PMID 27096957, 2016). "CXCR4 antagonists seem to regulate mTOR signaling in renal cancer cells, offering new therapeutic opportunities and targets to overcome resistance to mTOR inhibitors." (PMID 27891093, 2016). "The entire axis CXCR4–CXCL12–CXCR7 regulates the mammalian target of rapamycin (mTOR) signaling in renal cancer cells, a pathway identified in several human malignancies and effectively blocked by peptide R in these cells." (PMID 27015814, 2016). "This was a surprising outcome, since mTOR inhibitors proved successful in other malignancies, including breast and renal cancer." (PMID 27096957, 2016). "The emerging perspective for mTOR inhibitors in RCC treatment involves combination therapies targeting both renal cancer cells and renal CSCs." (PMID 27891093, 2016). "Expression PheWAS shows that the Fh1 locus modulates mRNA expression levels of 113 mitochondrial proteins, in addition to eight genes linked to renal necrosis, and seven genes involved in mTOR signalling, consistent with the known role of FH1 in renal cancer." (PMID 26833085, 2016).
renal carcinoma (continued). "Understanding the regulation of the mTOR pathway is of paramount importance in renal cancer as inhibitors of mTOR (everolimus and temsirolimus) which are structural analogs of rapamycin are clinically approved for the treatment of advanced metastatic cancer." (PMID 26255626, 2015). "Afterwards, the patient was treated clinically with antihypertensive drugs and new therapy for renal cancer consisting of temsirolimus, an inhibitor of the mammalian target of rapamycin (mTOR) pathway." (PMID 25351639, 2015). "On the opposite, CREB-1 activation together with mTOR inhibitors has also been described to potentiate chemotherapies in renal cancers." (PMID 26474850, 2015). "Aim of the study was to evaluate interactions between the CXCL12–CXCR4–CXCR7 axis and the mTOR pathway in human renal cancer cells to identify new therapeutic opportunities and overcome resistance mechanisms." (PMID 24991762, 2014). "In conclusion, the entire axis CXCR4–CXCL12–CXCR7 regulates mTOR signaling in renal cancer cells offering new therapeutic opportunities and targets to overcome resistance to mTOR inhibitors." (PMID 24991762, 2014). "As CXCR4–CXCL12–CXCR7 axis has been described to have a crucial role in renal cancer; the crosstalk between the mTOR pathway and the CXCR4–CXCL12–CXCR7 chemokine receptor axis has been investigated in human renal cancer cells." (PMID 24991762, 2014). "Although mTOR inhibitors are routinely used to treat patients suffering from renal cancer, substantial anti-tumour response has only been experienced by a subset of patients." (PMID 24779401, 2014). "Although we were unable to provide support for the value of FDG-PET as a clinically useful biomarker in the context of mTOR inhibition in renal cancer, a number of limitations should be recognized." (PMID 24156027, 2013). "To clarify the signaling pathways underlying simvastatin-mediated responses in renal cancer cells, we further examined the effect of simvastatin on the activation of the AKT/mTOR, pathways." (PMID 23690956, 2013). "Here, we first examined the role of mTOR in CNI-induced VEGF transcriptional activation in human renal cancer cells (786-0 and Caki-1)." (PMID 21886838, 2011). "Together, these observations suggest that CNI treatment and activation of the H-Ras pathway in human renal cancer cells can induce mTOR through increased phosphorylation of PRAS40." (PMID 21886838, 2011). "We have also shown that CNI-induced VEGF mRNA stability, and CNI-induced renal cancer cell proliferation are markedly inhibited following treatment with the mTOR inhibitor rapamycin (RAPA)." (PMID 21886838, 2011). "Moreover, immunoblotting was also used to investigate the regulatory effect of NCKAP1 on the PI3K/AKT/mTOR signaling pathway in renal cancer cells." (PMID 40141455, 2025). "The mTOR signaling pathway is notable for its central role in regulating cell growth, metabolism, and autophagy, and is closely related to the proliferation and survival of renal cancer cells." (PMID 39859168, 2025). "Furthermore, licochalcone A also induced autophagy by inhibiting the PI3K/AKT/mTOR signaling pathway in renal cancer 786-O and 769-P cells to alleviate renal carcinoma." (PMID 41357892, 2025). "In addition, in esophageal squamous cell carcinoma, TAM-derived CCL1 promotes tumor growth through the Akt/proline-rich Akt substrate of 40 kDa/mammalian target of rapamycin (mTOR) pathway, and in prostate, ovarian, and renal cancers." (PMID 39199574, 2024). "Additionally, RNF26 interacts with TSC1 and regulates the proliferation, migration, and angiogenesis of renal cancer cells through the mTOR signaling pathway." (PMID 38890443, 2024). "In addition, studies have found that the PI3K/AKT/mTOR signalling pathway is closely related to the malignant phenotype of renal cancer and plays an important role in the occurrence and development of renal cancer." (PMID 38169650, 2024).
renal carcinoma (continued). "Moreover, the PI3K/AKT/mTOR pathway is frequently hyperactivated in renal cancer, often in conjunction with VHL–HIF signaling, creating a distinctive therapeutic vulnerability." (PMID 39092291, 2024). "If the METTL3/AKT/mTOR signalling exists in renal cancer as well, the patients with overexpressed METTL3 might benefit more from everolimus." (PMID 36162823, 2023). "mTOR inhibitor everolimus is now applied in advanced renal cancer patients." (PMID 36162823, 2023). "Moreover, the activation of autophagy can be up-regulated by the inactivation of the phosphoinositide 3-kinase (PI3K)/protein kinase B (AKT)/mammalian target of rapamycin (mTOR) pathway in renal cancer or other tumors." (PMID 35740527, 2022). "High-level expression of POSTN can promote EMT via ILK/AKT/mTOR pathway in renal carcinoma." (PMID 35508298, 2022). "Modulation of PTEN/PI3K/AKT/mTOR signaling pathway could overcome the sunitinib resistance in renal cancer." (PMID 35081978, 2022). "In renal cancer, we observed the down regulation of mTor gene expression." (PMID 35163092, 2022). "Our experimental results demonstrated that p-mTOR was highly expressed in RMS and that the inhibition of mTOR in RMS cell lines promoted apoptosis and autophagy, and this finding was consistent with the idea that mTOR inhibited apoptosis and autophagy in renal carcinoma." (PMID 34221974, 2021). "The degree of miR-182 was markedly reduced in renal cancer tissue, while mTOR was upregulated." (PMID 33748185, 2021). "Given the established role of mTOR inhibitors as a pharmacological option in renal cancers, cathepsin K could be of use as a predictive marker of therapy response and as a potential target." (PMID 34069976, 2021). "In conclusion, the cross talk between HIF and mTOR/ERK-1/2 signaling pathways may regulate the aggressive properties of renal carcinoma in the AA population." (PMID 33996789, 2021). "A marked positive correlation between higher expression of LAT1 in renal cancers and frequent metastasis/poor prognosis may explain the significant effects of mTOR inhibitors on renal cancers." (PMID 34194623, 2021). "For example, it was reported that fluvastatin could potentiate the anticancer activity of vorinostat in renal cancer cells by activating the mechanistic target of rapamycin (mTOR) inhibitor (AMP)-activated protein kinase adenosine monophosphate (AMPK)." (PMID 34712689, 2021). "Thus, RAPA + Honokiol can act as a unique therapeutic combination to down-regulate the hyperactive Ras-mTOR pathway in renal cancer cells." (PMID 32635337, 2020). "Although we did not further investigate whether AMPK/mTOR pathway was activated by silibinin, AMPK/mTOR activation was reported to account for silibinin-triggered autophagic death in renal carcinoma cells." (PMID 32801360, 2020). "c-Met is a potent inducer of the mTOR pathway, which is hyper active in renal cancer." (PMID 32635337, 2020). "In renal carcinoma, activation of mTOR signaling promoted cell invasion ability by inducting EMT." (PMID 33293473, 2020). "Since the PI3K/AKT/mTOR pathway negatively regulates autophagy, effective renal cancer cell treatment with mTOR inhibitors (such as TEMS) may thus be antagonized by the resulting increased cellular protective autophagy." (PMID 32492043, 2020). "Notably, the mTOR inhibitor such as everolimus has been used as a second-line treatment in advanced renal cancer." (PMID 31950034, 2019). "Furthermore, we cannot exclude the possibility that mTOR-Is are permissive for some tumor entities while inhibiting others as has been postulated for prostate and renal cancers." (PMID 29659588, 2018). "Interestingly, mTOR also shows circadian rhythms in human osteosarcomas, mouse renal carcinomas as well as human breast cancer cells." (PMID 30250482, 2018).